BRCA2 (BRCA2 DNA repair associated)
Diseases named in the same sentence as BRCA2 in open-access papers (continued):
Sharing a sentence is not in itself a finding about the gene and the disease.
ovarian carcinoma (continued). "The relationship between both BRCA2 and MAGEC3 protein expression and their combined clinical significance in ovarian carcinoma is unknown." (PMID 36230652, 2022). "Given the BRCA2 results, we explored further, whether CRISPR-Select may be used for molecular diagnosis of hereditary breast and ovarian cancer." (PMID 36471068, 2022). "Studies conducted by Tsibulak showed higher BRCA1 and BRCA2 mRNA expression in ovarian cancer tissues compared with non-cancerous tissue." (PMID 35807169, 2022). "Mutations in BRCA1, BRCA2, RAD51C, and PALB2 genes were already shown to correlate with the risk of ovarian cancer, but not with BOTs." (PMID 35313928, 2022). "In this study ovarian cancer onset was 8–11 years earlier for BRCA1 patients compared to patients in BRCA2 and non-BRCA group." (PMID 35469032, 2022). "Notably, a familial history of breast or ovarian cancer was reported in 95 (49.7%) and 24 (32%) patients (BRCA1 and BRCA2, respectively); conversely, personal history of previous cancer was reported in only three (1.1%) patients." (PMID 36011033, 2022). "Any family history of ovarian cancer (irrespective of number of affected family members) was associated with a germline BRCA1 variant (OR, 2.78; 95% CI, 1.59-4.87; P < .001) but not BRCA2 (OR, 1.36; 95% CI, 0.47-3.97; P = .57)." (PMID 33646313, 2021). "In conclusion, we have confirmed that PARP1 is essential for HR in ovarian cancer cell lines lacking BRCA2 and treatment with rucaparib, a PARP inhibitor, increases the formation of γ-H2AX foci." (PMID 34572083, 2021). "Poly-ADP ribose polymerase inhibitor have emerged as exciting new chemotherapy options for women with ovarian cancer, especially for patients with BRCA1 or BRCA2 mutations or non-functional homologous recombination repair pathways." (PMID 34512721, 2021). "As a comparison in a recent study with an extended targeted panel, including 64 hereditary cancer predisposition genes, PV detection rate of 19.2% was reported in 496 patients with hereditary breast and ovarian cancer and 12% patients were positive for a PV in BRCA1 and BRCA2 genes." (PMID 34326862, 2021). "Other mutations, namely c.19_47del, c.668dupA, c.915T>A, c.2418dupA, c.2433delC, c.5030_5033delCTAA in BRCA1 and c.249delG, c.632-1G>A in BRCA2 do not overlap with previously reported breast or ovarian cancer cluster regions." (PMID 34490083, 2021). "Further to this, genetic risk factors such as the presence of established predisposition genes for hereditary breast and ovarian cancer (e.g. BRCA1, BRCA2) have not been found to be prevalent in Jamaican women, compared to other Caribbean countries." (PMID 33892714, 2021). "The ovarian cancer risk was associated with mutations in BRCA1, BRCA2, RAD51C, and PALB2 but not in the CHEK2 gene." (PMID 33670479, 2021). "In addition, oncogenic miR-1180, miR-493-5p, and miR-31 confer DDP resistance to ovarian cancer cells through silencing secreted frizzled-related protein 1(SFRP1), BRCA2, and potassium calcium-activated channel subfamily M alpha 1 (KCNMA1), respectively." (PMID 34512721, 2021). "Among ovarian cancer patients more than 9% harbored PVs in BRCA1 and BRCA2 genes." (PMID 34326862, 2021). "Although three studies utilised data from whole-exome sequencing (WES) of BRCA1 and BRCA2-negative ovarian carcinoma patients, these analysed only a subset of candidate genes in the available data and included non-HGSOC tumour types in their case cohorts." (PMID 32242007, 2020).
ovarian carcinoma (continued). "Much is still also not known about the influence of individual genes on risk of ovarian cancer especially the contribution not explained by the BRCA1 and BRCA2 genes and the role of single nucleotide polymorphisms." (PMID 31099061, 2020). "For ovarian cancer, somatic tumor profiling of BRCA1 and BRCA2 for PARP inhibitor therapy may reveal inherited germline mutations in these genes." (PMID 31937368, 2020). "Testing of unselected ovarian cancer cases in non-Ashkenazi Jewish populations shows that the frequency of deleterious BRCA1 and BRCA2 variants ranged from 3–10% and 0.6–6%, respectively." (PMID 33086730, 2020). "We found that three women with ovarian cancer (II1, II3, and II5) in the family carried BRCA1 (3326A>T) and BRCA2 (1342A>C) mutations, and no BRCA1 and BRCA2 mutations were detected in healthy individuals." (PMID 32356124, 2020). "The prospective cohort study of the German Consortium Hereditary Breast and Ovarian Cancer (GC-HBOC) is conducting the HerediCaRe registry, which is part of the International BRCA1 and BRCA2 Carrier Cohort Study (IBCCS), one of the largest registries for hereditary breast and ovarian cancer." (PMID 32140806, 2020). "In a recent work, absence of LOH was observed in 7% of BRCA1 and 16% of BRCA2 ovarian tumors and was correlated with decreased overall survival in ovarian cancers treated with platinum chemotherapy." (PMID 32850417, 2020). "Similarly, an international prospective study in the United States, Italy, and Spain found that ovarian cancer patients were highly satisfied with oncology clinic-based genetic testing for BRCA1 and BRCA2." (PMID 32028617, 2020). "The recognition of strong familial clustering of breast and ovarian cancer, followed by the discovery of the BRCA1 and BRCA2 (BRCA1/2) genes in 1994 and 1995, respectively, has led to the study and characterization of BRCA1/2-related hereditary breast and ovarian cancer syndrome (HBOC)." (PMID 31892343, 2019). "We documented 2923 women with ovarian cancer (BRCA1: 2319; BRCA2: 604)." (PMID 31213659, 2019). "The striking sensitivity of tumors lacking BRCA1 and BRCA2 is exploited in the treatment of breast and ovarian cancers with PARPi." (PMID 31632280, 2019). "Only one study reported BRCA1 among ovarian cancer and no studies reported BRCA2 among ovarian cancer patients, so heterogeneity was not assessed." (PMID 30898109, 2019). "It was also reported that BRCA2-negative ovarian cancer cells are more sensitive to cisplatin treatment." (PMID 31014274, 2019). "Based on a summary and analysis of 26 observational studies that included 3879 invasive epithelial ovarian cancers, the 5-year survival rates for BRCA1 mutation carriers, BRCA2 mutation carriers and noncarriers were reported as 44, 52 and 36%, respectively." (PMID 31472684, 2019). "Ovarian cancers were observed in 14 cases (BRCA1; 9, BRCA2; 5)." (PMID 29176636, 2018). "However, based on the age‐specific incidence rates of breast and ovarian cancer, we recommend bilateral oophorectomy at age 35 in BRCA1 carriers and at age 40 in BRCA2 carriers." (PMID 29266833, 2018). "PIN1 knockdown suppressed LYN Y397 phosphorylation in COV 362 cells (BRCA1 mutant ovarian carcinoma) and PEO-1 and PEO-4 cells (BRCA2 mutant ovarian carcinoma), but not in KURAMOCHI cells (BRCA2 mutant ovarian carcinoma)." (PMID 30590041, 2018).
ovarian carcinoma (continued). "Sequencing of BRCA1 and BRCA2 genes from tumors of 50 Mexican patients with ovarian cancer was made in a retrospective, non-randomized, and exploratory study." (PMID 29997359, 2018). "There is no international consensus up to which age women with a diagnosis of triple-negative breast cancer (TNBC) and no family history of breast or ovarian cancer should be offered genetic testing for germline BRCA1 and BRCA2 (gBRCA) mutations." (PMID 29514593, 2018). "The corresponding ovarian cancer risks are 16–68% for BRCA1 carriers and 11–30% for BRCA2 carriers." (PMID 28985766, 2017). "Thus, with the list of associated gene mutations evolving, more women can be expected to carry some mutation pre-disposing them to ovarian cancer and overall will exceed the 15% of all ovarian cancers attributed to BRCA1 and BRCA2." (PMID 28406427, 2017). "Lifetime risks for ovarian cancer are up to 44% and 27% for BRCA1 and BRCA2, respectively." (PMID 28157161, 2017). "Among women at high risk of breast and ovarian cancer who have previously tested negative for pathogenic BRCA1 and BRCA2 mutations, we identified three groups of women who should be considered for subsequent multi-gene panel testing." (PMID 28281021, 2017). "In five of the 51 ovarian cancer patients without a germline BRCA1 or BRCA2 mutation included in this study, a somatic, pathogenic mutation affecting BRCA1 or BRCA2 was encountered." (PMID 27767231, 2017). "Regulatory approval of olaparib for the treatment of advanced ovarian cancer is based on results of a nonrandomized phase II trial of 298 patients with solid tumors and germline BRCA1 or BRCA2 mutations, including 193 patients with recurrent ovarian cancer." (PMID 27983698, 2016). "BRCA1 and BRCA2 germline mutations are known risk factors for ovarian cancer, and it has been reported that up to 44% of patients without a family history of ovarian cancer harbour a germline BRCA1 or BRCA2 mutation, and as such may act as first alert for descendants." (PMID 26745875, 2016). "In addition, we found that combined inhibition of BRCA2 and PARP1 in vivo delayed the growth of ovarian cancer tumors." (PMID 26959114, 2016). "The majority of BRCA1 (18/18) and BRCA2 (19/22) carriers were identified from the patients without family history of breast or ovarian cancer." (PMID 27257965, 2016). "Although BRCA1 and BRCA2 mutations account for only ∼27% of the familial aggregation of ovarian cancer (OvC), no OvC risk prediction model currently exists that considers the effects of BRCA1, BRCA2 and other familial factors." (PMID 26025000, 2015). "Overall, significantly less ovarian cancer is seen in PALB2 families when compared with BRCA1 and BRCA2 families; therefore, it remains to be seen whether ovarian cancer risk is truly increased in individuals who are PALB2 mutation carriers or not." (PMID 26075229, 2015). "There are no doubts about the importance of methylation pattern in BRCA2 promoter region in breast and ovarian carcinoma." (PMID 25027116, 2014). "A patient diagnosed with ovarian cancer in her 4th decade and a strong family history of breast and ovarian cancer had previously tested negative for deleterious BRCA1 and BRCA2 mutations by another commercial lab." (PMID 24830819, 2014). "We also carried out MLPA analysis in 132 index cases from BRCA1/BRCA2-negative families with breast and/or ovarian cancer with either a personal or familial history of pancreatic cancer." (PMID 23935836, 2013).
ovarian carcinoma (continued). "RAD51C was investigated as a possible breast and ovarian cancer susceptibility gene in 1100 high-risk families, who were previously tested negative for BRCA1 and BRCA2 mutations." (PMID 23586058, 2013). "Women who have inherited genetic mutations have substantially increased risk of ovarian cancer, with a lifetime risk that varies with the genetic defect (for BRCA1, 30%–60%, for BRCA2, 15%–30% and for hereditary non-polyposis colon cancer, 7%)." (PMID 23591842, 2013). "Overall, of the 110 women who developed TNBC and were analyzed (63 with and 47 without family history of breast and ovarian cancers), 23 BRCA1 and 4 BRCA2 carriers were identified, giving a mutation prevalence of 24.5%." (PMID 23116406, 2012). "If larger studies confirm our findings, TNBC therefore may be included within clinical criteria for BRCA1 and BRCA2 mutation screening, and additional cases may be assessed not only if they present with early-onset of the disease or have a familial aggregation of breast and/or ovarian cancer." (PMID 22666503, 2012). "Though a subset of breast and ovarian cancers are associated with germline BRCA1 or BRCA2 mutations, the majority are sporadic and do not have BRCA1 or BRCA2 mutations." (PMID 22792303, 2012). "Clinical evidence suggests that the use of PARP inhibitors is not restricted to BRCA1 or BRCA2 mutated cancers, but that it also targets non-BRCA mutated ovarian cancer and can be useful in combination therapy." (PMID 24970153, 2012). "Nevertheless, whole-genome CNV profiling of patients fulfilling criteria for hereditary breast and ovarian cancer, but without BRCA1/BRCA2 mutations, has not been reported." (PMID 22314128, 2012). "This suggests that, regardless of the TNBC status, in the absence of family history of breast or ovarian cancer in this age group, a low (<10%) probability exists of having a BRCA1 or BRCA2 mutation." (PMID 23116406, 2012). "In the current study, we screened for RAD51C mutations in a clinic-based set of women with breast and/or ovarian cancers in families with HBOC who had previously tested negative for BRCA1 and BRCA2 mutations." (PMID 21980511, 2011). "BRCA2-deficient cancer cells are hypersensitive to DNA-crosslinking agents including cisplatin, as a consequence, women with BRCA1/2-mutated ovarian carcinoma have a better diagnosis than those without BRCA1/2- mutation if they receive platinum-based therapy." (PMID 21385444, 2011). "The BRCA2 gene is responsible for a high number of hereditary breast and ovarian cancers, and studies of the BRCA2 biological functions are limited by the lack of models that resemble the patient's tumour features." (PMID 20877358, 2010). "Similarly, in breast and ovarian carcinoma cell lines, BRCA1 and BRCA2 mRNA are concordantly induced by adriamycin, ionizing radiation, and estrogen." (PMID 19602291, 2009). "In a recent study, members of 283 epithelial ovarian cancer families from the United Kingdom (UK) and the United States (US) were screened for coding sequence changes and large genomic alterations (rearrangements and deletions) in the BRCA1 and BRCA2 genes." (PMID 19536330, 2009). "Recurrent ovarian carcinomas commonly have increased BRCA1 and/or BRCA2 protein expression post chemotherapy exposure which could mediate resistance to platinum based therapies." (PMID 19602291, 2009). "In light of previous studies showing that promoter hypermethylation of BRCA2 is rarely if ever encountered in ovarian carcinoma, we did not undertake similar studies on the BRCA2 promoter." (PMID 18208621, 2008).
ovarian carcinoma (continued). "Each of these cases, from the kConFab familial cancer repository, had a family history of breast or ovarian cancer with BRCA1-like breast pathology as defined by kConFab criteria, but were negative for mutations in the coding regions of BRCA1 and BRCA2." (PMID 18269736, 2008). "Penetrance for breast and ovarian cancer by age for BRCA1 and BRCA2." (PMID 18513387, 2008). "A deleterious mutation was detected in 20 out of 77 healthy, unaffected probands (26%; 15 in BRCA1 and 5 in the BRCA2 gene) with a severe family history of breast and/or ovarian cancer but no living affected relative." (PMID 18489799, 2008). "There are very significant nongenetic effects on breast and ovarian cancer risk in BRCA1 and BRCA2 carriers." (PMID 17213823, 2007). "With the prevalence of aberrations in the expression of TACC3 in the ovarian tumor arrays, we screened the coding sequence of the TACC3 gene in 76 ovarian cancer families that do not have mutations in known ovarian predisposition loci, such as BRCA1 and BRCA2." (PMID 15918899, 2005). "The corresponding ovarian cancer risks were 32.8% for BRCA1 and 17.8% for BRCA2." (PMID 11857015, 2002). "The corresponding ovarian cancer risks were 25.9% for BRCA1 and 9.1% for BRCA2." (PMID 11857015, 2002). "The dominantly inherited ovarian cancer predisposing genes, BRCA1, BRCA2 and genes involved in the hereditary non-polyposis colorectal cancer (HNPCC) syndrome, have recently been identified." (PMID 9652774, 1998). "Guidelines from the American Society of Clinical Oncology (ASCO) and the National Comprehensive Cancer Network (NCCN) recommend all women diagnosed with epithelial ovarian cancer undergo germline genetic testing for BRCA1 and BRCA2 and other susceptible genes, regardless of their family history." (PMID 40894326, 2025). "Notably, these observations are independent of both the BRCA2 status of the ovarian cancer cells (BRCA2 wildtype or BRCA2 mutant) and the G4 mapping technique used (BG4 ChIP-Seq or BG4 CUT&Tag)." (PMID 40646632, 2025). "When the RR was assumed to be independent of age, the estimated BRCA1 breast and ovarian cancer RRs (95% CI) were 15.6 (12.6–19.4) and 39.8 (29.6–53.3), respectively, and the estimated BRCA2 breast and ovarian cancer RRs (95% CI) were 10.3 (8.3–12.7) and 6.8 (3.9–11.9), respectively." (PMID 38333895, 2024). "The Lambda model estimates the probability that an Ashkenazi Jewish woman is a BRCA1/BRCA2 PGV carrier based on a point system, considering personal family history, whether she is a first-degree or second-degree relative with BC and ovarian cancer, age at diagnosis, and bilateral BC in the proband." (PMID 38672070, 2024). "Given that we did not observe upregulation of Tcf1/7, Myc, and cyclin D1 in BRCA2-null ovarian cancer cells, the potential absence of these prosurvival mechanisms may very well contribute to the improved survival observed in patients with BRCA2 ovarian cancer." (PMID 39028933, 2024). "Data from The Cancer Genome Atlas (TCGA) revealed that RAD18 mRNA is more highly expressed in BRCA1-mutated breast tumors, relative to BRCA2-mutated and WT tumors (left), although RAD18 mRNA expression does not appear to be significantly enriched in BRCA1-mutated ovarian carcinomas (right)." (PMID 38943334, 2024). "However, the expression of the tumor suppressors BRCA1 and BRCA2 were not significantly altered in ovarian cancer." (PMID 36305848, 2023). "Additionally, before 70 years of age, ovarian cancer may manifest in 39% of females with detrimental BRCA1 alteration and 11%–17% of females with BRCA2 alteration." (PMID 36971312, 2023). "Moreover, many other elements of care that are tumour-group-specific are absent from the QIs extracted; for example, BRCA1 and BRCA2 genetic testing to guide treatment decisions in ovarian cancer as per the Society of Gynaecologic Oncology." (PMID 37924649, 2023).